CD68 (CD68 molecule)
Diseases named in the same sentence as CD68 in open-access papers (continued):
Sharing a sentence is not in itself a finding about the gene and the disease.
ovarian carcinoma (42 papers, 2013 to 2025). A malignant neoplasm originating from the surface ovarian epithelium. "PD-L1 is widely expressed in tumor cells, tumor infiltrating lymphocytes, and tumor stromal cells, especially tumor-associated CD68+ macrophages in ovarian cancer." (PMID 35086548, 2022). "Accordingly, studies have reported that high ratios of intra-tumoral CD8/Tregs or CD68/CD163 macrophages were associated with improved overall survival in ovarian cancer." (PMID 32852603, 2021). "A study focused on ovarian cancer, for instance, unveiled a significant increase in both CD68 + TAMs and CD163 + TAMs density in advanced ovarian cancer, with CD163 + TAM infiltration being associated with an adverse prognosis in ovarian cancer patients." (PMID 38273373, 2024). "Of note, the density of CD68+YAP1high MΦs dramatically decreased from the primary EOC tumor at the early stage to omental metastases in advanced ovarian cancers." (PMID 39198883, 2024). "The expression of M1 and M2 markers was positively correlated with CD68 expression in the samples from ovarian cancer patients, demonstrating a correlation of these M1/M2 markers with the presence of macrophages." (PMID 37809073, 2023). "We compared the expression of CD68 in 85 cancer, 7 normal, and 35 benign ovarian tissues and found that the immunohistochemistry activity of CD68 is higher in the ovarian cancer tissues compared to that in the others." (PMID 36757936, 2023). "Tissues were divided into low and high groups based on the median value of CD68 expression in ovarian cancer tissues." (PMID 36757936, 2023). "Prostate cancer patients with a higher score of depression revealed higher CD68+ tumor-associated macrophage (TAM) infiltration, and daily restraint stress increased infiltration of CD68+ macrophages in rodent models of ovarian cancer as well." (PMID 34869378, 2021). "Some studies demonstrate high M2-like TAM (CD163+) levels in primary ovarian cancer tumors, and a high proportion of the CD163+/CD68+ TAM phenotype, is associated with poor PFS." (PMID 34677277, 2021). "PD-L1 expressing CD68 macrophage represent suppressor cell populations in ovarian cancer, which contribute to immune escape of ovarian cancer cells." (PMID 33415077, 2020). "Although IL-17 is secreted by CD4+ T cells and CD68+ macrophages in ovarian cancer, in other types of cancer, a population of FoxP3+ regulatory T cells (Treg), that under certain conditions express IL-17, plays a critical role in the regulation of CSCs." (PMID 28819364, 2017). "Xiang and collaborators demonstrated that IL-17 in ovarian cancer is produced by CD4+ T cells and CD68+ macrophages, tumor-associated macrophages (TAM) in the ovarian CSC niche, and the IL-17 receptor is expressed in a population of CD133+ CSCs." (PMID 28819364, 2017). "IL-6 positive cells were also CD-68 positive, suggesting that IL-6 expressing cells surrounding ovarian cancers are mainly macrophages." (PMID 25658637, 2015). "The TAMs in the ovarian cancer specimens were quantitatively analyzed based on CD68 single immunostaining." (PMID 24324582, 2013). "Moreover, we analyzed the Cancer Genome Atlas Ovarian Cancer (TCGA-OV) database, and found CD68+YAP1low groups exhibited dramatically increased M2-like TAMs markers expression, such as MMP9, CCL8, SPP1 and CCL17, when compared to CD68+ YAP1high." (PMID 39198883, 2024). "In clinical samples of ovarian cancer, PD-L1+ CD68+ macrophages have been elucidated to express higher levels of IL-10, IL-6, compared to PD-L1- CD68+ macrophages; moreover, PD-L1 binding to T cells PD-1 has been demonstrated to induce apoptosis of T cells, thereby facilitating immune escape." (PMID 37313405, 2023).
ovarian carcinoma (continued). "Studies analyzing the association between TAM infiltrates and prognosis have used various measures (i.e. CD163, CD68, M1/M2 ratio) and a meta-analysis in ovarian cancer (histologies combined) found that only the M1/M2 ratio was significant for both overall and progression free survival." (PMID 36368129, 2023). "Besides, the expression of M1/M2 markers was positively correlated with a pan-macrophage marker (CD68) in ovarian cancer patients at the protein level." (PMID 37809073, 2023). "Many studies about the impact of NAC on TIME in ovarian cancer have been published, and have generally demonstrated that the levels of CD3/CD8 T cells and CD68 tumor-associated macrophages increased after NAC, while Foxp3 regulatory T cells decreased after NAC." (PMID 35565437, 2022). "In ovarian cancer patients, the five-year overall survival rate was significantly lower in OC patients with high percentages of CD68+ TAMs (>14.5%) in spheroids compared with low percentages (<14.5%) of CD68-positive cells." (PMID 35682890, 2022). "In 112 ovarian cancer patients from the Chinese cohort, intratumoral CD68+ TAM density significantly increased with increasing cancer stage and grade, however, displayed no prognostic significance in both the Kaplan–Meier survival and multivariate Cox regression analyses." (PMID 33194645, 2020). "In lung and ovarian cancer, the major parameter associated with prognosis was not the total amount of CD68+ macrophages, but M1/M2 index." (PMID 33194645, 2020). "In peripheral blood of 51 patients with pathologically diagnosed ovarian cancer the proportion of PD-L1+ CD68+ cell among CD68+ cells and the intensity of PD-L1 staining on CD68+ cell were significantly higher in the ovarian cancer group in comparison with the healthy group." (PMID 33194645, 2020). "Within these hetero-spheroids, CD68+ macrophages (derived from U937 or peripheral blood monocytes) make up ~ 20% of the population, while the rest are ovarian cancer cells and ovarian cancer stem cells (derived from the high grade serous ovarian cancer cell line, OVCAR3)." (PMID 31324218, 2019). "The majority (87.8%) of CD11b+CD14+ cells were CD-68, a surface marker of macrophages, and CD-206, a surface marker of positive M2-polarized macrophages, suggesting that IL-6 producing cells in ovarian cancer ascites are predominantly M2-polarized macrophages, TAMs." (PMID 25658637, 2015). "To establish the relationship between the COX-2 expression level and the differentiation status of the TAMs, we used a triple-immunostaining technique to determine the M1- and M2-differentiation patterns of the CD68+COX-2+ TAMs that had infiltrated the ovarian cancer tissues." (PMID 24324582, 2013). "While all co-cultures resulted in the production of CD68+ macrophages, the number varied considerably across the five HGSOC cell lines, consistent with the heterogeneity observed in ovarian cancer." (PMID 33069212, 2020). "In this exploratory study, we aimed to determine the tumor anatomy-attributed expression pattern of the top 3 candidate molecules – CD68, SMPD1, and LPAR3 – within complex ovarian cancer tissues." (PMID 31049165, 2019). "Herein, we focused and explored predominantly the observational findings highlighting similarities in expression patterns for CD68 and SMPD1 (also known as acid sphingomyelinase, ASMase, ASM) in macrophage/monocyte lineage cells within the ovarian cancer tissue." (PMID 31049165, 2019). "To test this hypothesis, we analyzed M1 macrophage markers, including CD80, CD32, and CD64, and M2 macrophage markers, including CD68, CD206, and CD163, in HERV-K119 env KO THP-1 cells and compared them with those in HERV-K119 env KO OVCAR3 ovarian cancer cells." (PMID 37958549, 2023).
ovarian carcinoma (continued). "In addition, daily restraint stress increased ovarian cancer growth, infiltration of CD68+ macrophages, and expression of PDGF-AA in orthotopic models of ovarian cancer (SKOV3ip1 and HeyT30), while zoledronic acid, a macrophage-depleting agent, abrogated this effect." (PMID 32962103, 2020). "Interestingly, our results demonstrated that production of CD68+ macrophages by ovarian cancer cells was independent of MCSF." (PMID 33069212, 2020). "Indeed, CD68 and CD163 are both used to identify macrophages in tissue sections, but while CD68 is commonly used as a pan-macrophage marker, CD163 is regarded as a highly specific marker for M2-polarized macrophages in several human tumors, including ovarian cancer." (PMID 27462782, 2016). "Indeed, CD68 and CD163 are both used to identify macrophages in tissue section, but while CD68 is commonly used as a pan-macrophage marker, CD163 is regarded as a highly specific marker for M2-polarized macrophages in several human tumors, including ovarian cancer." (PMID 26797759, 2016). "In the ovarian cancer tissue itself, no dendritic cells, 30% of CD45 positive cells, 15% of CD11b positive cells, and no CD68 positive cells were found (for a summary of the results)." (PMID 33921688, 2021). "In the ovarian cancer tissue itself, 20% of dendritic cells, 5% of CD45 positive cells, 20% of CD11b positive cells, and no CD68 positive cells were found." (PMID 33921688, 2021).
breast tumor (40 papers, 2008 to 2025). "And in HR+/HER2− breast tumors, higher level of CD68+ cells was associated with favorable response to neoadjuvant chemotherapy." (PMID 38133211, 2023). "We previously observed that in vivo inhibition of tumoral GRP78 increased breast tumor infiltrating CD68 macrophages and was associated with increased therapeutic responsiveness." (PMID 29113324, 2017). "In these tissues, CD68+ cells (TAMs) and Nile Red positive cells co-localized, thus further suggesting that excessive LD accumulation was presented in human breast tumor associated TAMs." (PMID 28974683, 2017). "Previous studies have shown that higher tumor grade and higher Ki67 index are associated with increased CD68+ macrophage infiltration in breast tumors." (PMID 26243145, 2015). "Next, we investigated the association between CD68, CD163, CD86, and PD-L1 expression and the clinicopathological features of primary breast tumors." (PMID 40510346, 2025). "In our study, we revealed that Cd68+ApoE+ cells were found in the TMEs of lung metastatic breast tumors were correlated with C1qa/b/c, Cd74, and ApoE expression." (PMID 39695088, 2024). "The slides showed that NR1H3 and CD68 protein were expressed in interstitial cells of breast tumor tissues." (PMID 36699456, 2022). "In our study, we have shown abundance of CD-68–positive macrophages in the inflamed breast tissues adjacent to the breast tumor confirming their role in tumor progression in companion with initiated epithelial cells." (PMID 34774800, 2022). "The results showed that CD206 was strongly positive, and CD68 was suppressed in breast tumor tissues compared with adjacent tissue." (PMID 34659411, 2021). "Immunohistochemical analysis of breast tumor tissues confirmed the co-localization of TREM1 protein expression with the pan-macrophage marker CD68." (PMID 33575478, 2021). "Patient samples were used to detect the phosphorylated Smad2 (the activated form of Smad2) and CD68 (a pan-macrophage marker) in breast tumor tissue using immunofluorescence staining." (PMID 32724475, 2020). "The current study showed increasing expression of CD68 (a marker for macrophage and monocyte) on breast tumors exposed to ECCT (IT group), which was significantly higher than non-EF therapy (INT)." (PMID 32695310, 2019). "We show here that primary breast tumors and sentinel lymph nodes from clinical samples from patients overexpress p32 protein and that the number of CD68+ macrophages is increased compared with healthy tissues." (PMID 29721153, 2018). "In agreement with the present data, previous studies reported that fibroblasts isolated from normal skin, normal breast, and breast tumor tissue clearly expressed CD68 protein at levels comparable to macrophages." (PMID 28178651, 2017). "Immunohistochemical staining of human primary breast tumors for CD68, a pan-macrophage marker, and OPG revealed that of the 46 samples tested 95.7 and 78.3%, respectively, exhibited moderate/strong staining for these markers." (PMID 28143606, 2017). "Notably, 89% of tumors (171/193) were positive for CD68, indicating the ubiquitous presence of macrophages in breast tumors." (PMID 38968186, 2024). "Moreover, CD68 expression was increased tumor tissues compared to that in nontumor tissues, suggesting that macrophages aggregated in the breast tumor tissues." (PMID 37249285, 2023). "In addition, CD206 was strongly positive and CD68 was suppressed in breast tumor tissue, indicating that the immune microenvironment in the tumor tissue was changed." (PMID 34659411, 2021). "In addition, we also examined the levels of proinflammatory cytokines such as IL12/IL6, expressed in circulating macrophages (CD68), which also accumulate in a breast tumor microenvironment." (PMID 33414685, 2020). "Additionally, increased number of CD68-positive cells was found in breast tumors and in sentinel lymph nodes, both from patients with and without metastases, in comparison to healthy breast." (PMID 29721153, 2018).
breast tumor (continued). "This may be, in part due to increased angiogenesis that has been shown in mouse models of mammary gland tumors and in human breast tumors where CD68 levels correlate with VEGF expression." (PMID 23741308, 2013). "As in the breast tumours, the oval or irregular shape and the kidney-shaped nucleus that has a prominent nucleolus located at the nuclear membrane are the histopathological features that together with CD68 positivity enabled us to identify them as macrophages." (PMID 19014637, 2008). "Next, we analyzed the impact of CD68, CD163, CD86, and PD-L1 expression on recurrence-free survival (RFS), defined as the time between the initial diagnosis of the primary breast tumor and cerebral progression." (PMID 40510346, 2025). "In the case of double IHC, breast tumor cells demonstrated nuclear PELP1 expression (3,3′-diaminobenzidine; brown) and CD68 expression (Alk magenta) in the cytoplasm, indicating macrophages." (PMID 34774800, 2022). "For further differentiation, we stained FFPE tissue sections from primary human breast tumors of our patient cohort with pan‐cytokeratin for tumor cells, αSMA to identify fibroblasts, and CD163, CD68, and CD206 to mark macrophages." (PMID 33377644, 2020). "The potential causative link between macrophages and elevated OPG levels were further supported by the immunohistochemical analyses of pan-macrophage marker CD68 and OPG which indicated a co-occurrence of these two markers in human primary breast tumors." (PMID 28143606, 2017). "We used breast tumor tissues from each patient to make tissue microarrays that were then stained for leukocyte and myeloid markers including CD4, CD8, CD20, CD25, CD68, and CD163 using immunohistochemical techniques." (PMID 28794686, 2017). "Macrophage infiltration (CD68) and activation status (HLA-DRIIα, CD163) were evaluated in a large cohort of human primary breast tumors (562 tissue microarray samples), by immunohistochemistry and scored by automated image analysis algorithms." (PMID 26243145, 2015). "Triple-negative/basal-like breast tumor stroma had more CD163+ and CD68+ cells and a higher proportion of CD163 relative to CD68 when compared to the stroma of luminal A tumors." (PMID 26243145, 2015). "The three off-the-shelf panels for human tissue were Tact (CD3, Ki67, Granzyme B and PanCK), PD-L1 (CD8, CD68, PD-L1 and PanCK) and APC (CD11c, CD20, CD68+CD163 cocktail and MHCII) panels, which were evaluated on human breast tumor specimens with varying levels of T cell density." (PMID 38605049, 2024). "Breast tumors infiltrated by MMP-11+ mononuclear inflammatory cells are more likely to metastasize, have high levels of interleukin (IL)-1, IL-5, IL-6, IL-17, interferon (IFN), and NFB, and an increased CD68+/(CD3+CD20+) cell ratio at the invasive front." (PMID 39190284, 2024). "To assess the expression of PELP1 in macrophages present in tumor milieu, we analyzed the expression of CD68, a macrophage-specific marker along with PELP1 in serial sections of inflammatory breast tumor tissues (N = 13) by double immunohistochemistry (IHC) staining and double immunofluorescence." (PMID 34774800, 2022). "Moreover, immunofluorescence staining of frozen breast tumor sections from tumor-bearing mice receiving CSSTRESAC-phage iv suggested co-localization between PDIA3 and CD68, a well-established cell surface marker of macrophages." (PMID 34060472, 2021). "To evaluate the potential relationship between cancer cells with mesenchymal features and the presence of TAMs in breast tumor stroma, we selected 30 relevant EMT-related kinases and correlated their expression with the expression of the pan-macrophage marker CD68 in a cohort of 203 TNBC patients." (PMID 28721387, 2016).
breast tumor (continued). "On the other hand, these authors also showed that macrophages at the tumor–stroma border could be identified as migratory CD68+CD206negdextranneg myeloid cells and sessile CD68+CD206+dextran+ M2-type TAMs, representing the existence of distinct macrophage types in breast tumors, as well." (PMID 37958292, 2023). "B7H4-positive cells were found in the CD45-negative cell population in breast tumor tissues, and no surface B7H4 expression was detected in tumor-associated macrophages (CD45+CD68+ cell population) and tumor vasculature (CD45−CD31+ cell population) (data not shown)." (PMID 31848656, 2020). "Furthermore, staining wild-type or GRP78 heterozygous breast tumors with CD68 (green) and CD80 (red) indicates that GRP78 heterozygousity increases the CD68+/CD80+ double positive cell infiltration into the breast tumor, suggesting an elevated tumoral M1-like macrophage population." (PMID 29113324, 2017).